INS (insulin)
Diseases named in the same sentence as INS in open-access papers (continued):
Sharing a sentence is not in itself a finding about the gene and the disease.
diabetes (continued). "Finally, they remarked that a patient with known diabetes is more likely to receive insulin therapy, although almost two-thirds of the patients hospitalised for ACS with hyperglycaemia at admission showed impaired glucose tolerance (IGT) or a newly diagnosed diabetes at three months after discharge." (PMID 33466656, 2021). "Type 1 diabetes mellitus is a common chronic, metabolic disease characterized by high fasting glucose, in which beta cells from the islets of Langerhans in the pancreas can no longer produce insulin, needed to maintain blood glucose levels in the range of 4.0–5.5 mmol/L." (PMID 34490230, 2021). "In addition, fasting blood insulin and insulin resistance in the MJ2 significantly low compared with the hkMJ2, which suggested that live P. freudenreichii MJ2 might be more effective in improving diabetes." (PMID 33510408, 2021). "Similarly, the observed increased risk of the composite outcome of any surgical interventions due to DPP4i was more apparent in patients with relatively shorter diabetes duration, and those who took sulfonylurea, and those without insulin therapy (All p-values for interaction <0.05)." (PMID 34203446, 2021). "Experimental studies suggest that pioglitazone may upregulate ACE2 in insulin-sensitive tissues and, although this effect in the lung is still uncertain, this supposed increase in ACE2 expression has raised some concerns about the use of this drug in patients with diabetes and COVID-19." (PMID 34031865, 2021). "In the macrosomia group, there were also more cases of primiparous women, cases of gestational diabetes mellitus (GDM) including diabetes treated with insulin (GDM-2), as well as family history of diabetes mellitus (DM), but these differences were insignificant." (PMID 33671089, 2021). "Therefore, while oral medications were available for patients with known diagnoses, diagnosis and management (using insulin) for diabetes could not be fully supported through IRC-supported facilities." (PMID 33777712, 2021). "However, since diabetes in Swiss Webster mice appears to be due to beta-cell dysfunction that is not secondary to insulin resistance, excess HFO intake in early life may have adversely affected long-term beta-cell function and survival." (PMID 34234216, 2021). "Some studies reported that CFRD patients have lower GIP and GLP-1 levels than patients without diabetes and control groups, and this could contribute to the postprandial glycemic variability present in CFRD, associated with impaired first-phase insulin release." (PMID 33810109, 2021). "The term “diabetes” actually covers a group of metabolic disorders characterized by high blood glucose levels over a period of time, and it is the result of the pancreas producing insufficient insulin (type 1), or the cells of the body not responding properly to the insulin produced (type 2)." (PMID 34063354, 2021). "The first one is that patients with diabetes may have a higher likelihood of receiving insulin therapy in comparison to patients without the disease, possibly attenuating the rise in plasma free fatty acids (FFA) as well as providing antithrombotic properties associated with its use." (PMID 33463901, 2021). "Taking into account that the animal model of diabetes used in this study is characterized by partial destruction of pancreatic beta cells and not insulin resistance, it could be that ODSO stimulates peripheral tissues to store glucose or potentiates the effect of insulin." (PMID 33918827, 2021). "Diabulimia is a term, derived from diabetes mellitus (DM) and bulimia, for an eating disorder (ED) characterized by the intentional reduction or omission of a dose of insulin without consulting a doctor, in order to control weight." (PMID 34371885, 2021).
diabetes (continued). "Additionally, conophylline administration (0.9 mg/kg/day, oral gavage) for 4 weeks improved glucose tolerance, increased pancreatic insulin, reduced islet fibrosis, and increased the number of MafA-positive β-cells in Goto-Kakizaki rats, a non-hypertensive model of diabetes." (PMID 35098034, 2021). "Among 33,171 patients with diabetes, 2,269 (6.8%) were untreated prior to PCI admission, 2,049 (6.2%) were controlling diabetes through diet only, 16,396 (49.6%) were treated with oral agents without insulin, 12,205 (36.8%) were treated with insulin, and for 252 (0.8%) the treatment was unknown." (PMID 34106945, 2021). "Diabetes mellitus (DM) is an endocrine disorder that is characterized by hyperglycemia in response to absent or inadequate insulin secretion or impairment of insulin action." (PMID 33927613, 2021). "While the significant reduction of insulin-specific CD4+ and CD8+ T cells in TIP-1 is suggestive of deletional tolerance, it is possible that transgenic antigen expression in APCs may induce regulatory T cells (Tregs) that confer dominant tolerance and prevent diabetes in TIP-1 mice." (PMID 33841427, 2021). "However, although the OR animals presented altered values of insulin and area under the glycemic curve, these animals did not present higher fasting glucose values that could characterize diabetes." (PMID 34287576, 2021). "Whilst encouragingly we are seeing growing utilisation of long-acting insulin analogues in a number of LMICs including Bangladesh, India and Malaysia (section Asia), reflecting their increasing role and value in managing patients with diabetes, this is not universal." (PMID 34249838, 2021). "Indeed, most insulin-resistant individuals do not develop diabetes." (PMID 34843575, 2021). "However, when body mass index (BMI) and insulin levels were added to the model, the association between IGFBP-1 and diabetes was attenuated and no longer significant (HR 0.47, 95% CI 0.21–1.03, p = 0.06 in the overall cohort; HR 0.66, 95% CI 0.26–1.67, p = 0.38 in men)." (PMID 32492897, 2020). "Diabetes mellitus (DM), referred to simply as diabetes, is a metabolic disease that is due to either the pancreas not producing enough insulin or the cells of the body not responding properly to insulin." (PMID 33255227, 2020). "Furthermore, the time to diabetes diagnosis was longer in women without insulin treatment for GDM." (PMID 32725280, 2020). "Therefore, the role of pancreatic α-cells and glucagon secretion has been revisited and type 2 diabetes mellitus (T2DM) is considered as a bi-hormonal defect proposing that diabetic hyperglycaemia would not develop unless the lack of insulin was accompanied by hypersecretion of glucagon." (PMID 32218947, 2020). "Patients who had recently commenced insulin treatment or changed their pill-based regimen, found it difficult to get to care providers (due to impairment, social and/or economic related reasons), or had a history of non-attendance at clinics, were visited by a diabetes care technician." (PMID 32192474, 2020). "However, 16 weeks after diabetes induction and 12 weeks after treatment initiation, thermal hyperalgesia as evident by a decrease in latency was observed in animals receiving low-insulin or no insulin compared to control." (PMID 32832565, 2020). "It was found kaempferol ameliorates diabetes in a diabetic animal model, where treatment restored hexokinase activity in the liver and skeletal muscle of diabetic mice; and body weight, calorie intake, body composition, plasma insulin, and glucagon levels were not altered." (PMID 32694996, 2020). "The studies with sulfonylurea, metformin, insulin, and the thiazolidinediones provide support for the recommendation that improvement of glycemic control has long term benefits on ASCVD risk in both type 1 and 2 diabetes although they did not point to a clear target for this treatment." (PMID 33134327, 2020).
diabetes (continued). "Thus, a chronic insult from either no insulin in Type 1 diabetes or reduced signaling due to insulin resistance, such as that seen in Type 2 diabetes, may contribute to the pathophysiology of diabetes induced corneal endothelial damage." (PMID 32194500, 2020). "Third, individuals with diabetes in the study comprise a mix of type 1 and type 2 diabetes, which could not be methodologically distinguished due to potential misclassifications of ICD-diagnoses, i.e. an individual with insulin treated type 2 diabetes could be misclassified as type 1 diabetes." (PMID 32745121, 2020). "Specifically, compared with normal-weight mothers without diabetes, the pointwise effect size for mood disorders was 2 to 3 times higher for obese mothers with type 2 diabetes and was 3 to 8 times higher for obese mothers with insulin-treated pregestational diabetes." (PMID 32031649, 2020). "Overall, BIR is regulated by aberrant insulin signaling and may contribute to disordered glucose metabolism, oxidative stress, BBB dysfunction, and energy supply insufficiency, which are pathological features of diabetes mellitus that can further affect Aβ generation and clearance." (PMID 33250703, 2020). "Notably, the altered glucose sensing in pancreatic beta-cells, combined with lower insulin levels and higher blood glucose in CB2−/− mice, should be taken into consideration in view of the development of pharmacological cannabinoid receptor antagonists in diabetes therapy." (PMID 32365865, 2020). "Furthermore, an oral glucose tolerance test is a better predictor of cardiovascular events than a fasting plasma glucose evaluation, and those with abnormal glucose metabolism without a previous diagnosis of diabetes mellitus are more insulin-resistant than those with a healthy glucose metabolism." (PMID 32095319, 2020). "It has been hypothesized that some compounds of V could be used as substitutes for insulin in diseases such as diabetes; however, the latest reviews do not support this, since long-term treatment could cause toxicity due to the possible excess accumulation of V." (PMID 32916939, 2020). "Hence, despite being on insulin sensitizers, the target to control for their diabetes was not achieved, which could contribute to sarcopenia." (PMID 32433712, 2020). "However, in the current era, there still remains a lack of definitive evidence regarding the appropriate use of insulin in this setting, as well as a lack of insight into the effects of insulin use in patients without diabetes - both of which were found to be significant in our study." (PMID 33118731, 2020). "DM develops when insufficient or no insulin level is produced (Type 1 diabetes mellitus) or released insulin in the body does not function properly (Type 2 diabetes mellitus), resulting in hyperglycemia." (PMID 33255206, 2020). "Therefore, data related to the development of diabetes and decreased insulin secretion are lacking." (PMID 33318573, 2020). "Diabetes mellitus (DM) is a systemic metabolic disease, which is characterized by chronic hyperglycemia due to lack of insulin secretion, insulin action, or both." (PMID 32106580, 2020). "Indeed, reviews have highlighted how PH may benefit individuals with diabetes or those who are insulin resistant, but to date, there is no systematic search, review and meta-analysis of PH and glycaemic control in diabetic and non-diabetic individuals." (PMID 30901372, 2019). "Moreover, due to the incomplete data contained in original articles, some factors that greatly influence dental caries, including sex, diabetes mellitus duration and insulin treatment duration, could not be analyzed." (PMID 31521152, 2019). "In addition, the learning needs about illness and self-care, evidenced in the children’s voices, justified the implementation of this determinant: In diabetes, there is no insulin to kill sugar (...)because if it did not kill sugar, diabetes would always be high (Girl, 8)." (PMID 30916223, 2019).
diabetes (continued). "However, with self-monitoring of blood glucose levels, earlier research on diabetes management showed lack of evidence on the benefit of self-monitoring glycemic control for persons with type 2 diabetes not using insulin after their first year with their disease." (PMID 31492176, 2019). "In a diabetes prevention program study, 3007 subjects treated with metformin or troglitazone coupled with lifestyle changes for 1 year were genotyped and the results have shown that a genotype at SLC30A8 could predict baseline proinsulin levels independently of insulin levels." (PMID 30936916, 2019). "So far, the investigation of insulin–glucose metabolism variations in diabetes with and or without obesity on omentin expression in adipose tissue has not been performed, while some studies have mentioned that mice adipose tissue may not have an important role in the secretion of omentin." (PMID 31428203, 2019). "Although saved from death, the life of insulin-treated people with diabetes was not normalized, either on a daily basis, with unpredictable bouts of hypoglycemia and acidosis, or in the long term, as chronic complications of diabetes could now become manifest." (PMID 30357355, 2019). "Although he uses just basic functions of his insulin pump, he has no problem to operate any kind of device and could benefit from more advanced functions (eg, square wave or dual wave bolus, bolus wizard) in case he got proper education in diabetes management." (PMID 31290400, 2019). "In the progressive path to T2DM, insulin resistance continues to increase until insulin secretion from the pancreatic β-cell fails to compensate fully resulting in elevated blood glucose concentrations that eventually meet criteria for pre-diabetes (100–125 mg/dL, )." (PMID 31013914, 2019). "Diabetes mellitus consists of a group of metabolic disorders with an increased blood sugar level (namely hyperglycemia) due to either insufficient insulin production by the pancreas (type I diabetes) and/or cells not responding to insulin (insulin-resistant type II diabetes) in the body." (PMID 31115753, 2019). "The most important is that insulin treatment was not randomized and patients on insulin had longer standing diabetes, implying a greater severity of diabetes, and in turn there were substantial differences in baseline characteristics between patients treated with and without insulin." (PMID 31271255, 2019). "In this study, heat-killed S. thermophilus may also affect diabetes through the BMID axis by increasing the abundance of beneficial bacteria, protecting the intestinal epithelial barrier, and suppressing IL-6, LPS, and TNF-α secretion, and the end result is moderation of insulin tolerance." (PMID 31223540, 2019). "Thus, hypoglycaemia is ‘the limiting factor in diabetes therapy’6 and, if it were not for hypoglycaemia, diabetes could be easily managed simply by increasing the insulin dose until normoglycaemia is restored." (PMID 30635569, 2019). "Although all the types of diabetes result in high blood sugar levels over a prolonged period, Type 1 diabetes is said to be an autoimmune disorder which results in the destruction of insulin-producing pancreatic β-cells making it insulin dependent while Type 2 diabetes is non-insulin dependent." (PMID 31803711, 2019). "Diabetes Mellitus (DM) is a complex disease characterized by high levels of glucose (HG) in serum due to either lack of insulin production (type 1 DM) or malfunctions in its signaling (type 2 DM), with negative effects on several organs including the skeleton." (PMID 30783155, 2019). "Interestingly, a treatment based on oral insulin administration demonstrated a delay in the diabetes onset in Non-Obese Diabetic (NOD) mice, an animal model which has been heavily used to study the progression and pathogenesis of T1D, and which we will describe in the next section." (PMID 31561568, 2019).
diabetes (continued). "Likewise, the presence of diabetes may be important in the lack of greater hepatic insulin sensitivity in our black men, as per our hypothesis." (PMID 30729259, 2019). "Future investigations of the impact of FFA, insulin, hyperglycemia, as well as mitochondrial dysfunction on BAIBA production in muscles and other tissues will help to elucidate whether BAIBA plays a role in overcoming the elevation of plasma FFA and glucose in diabetes." (PMID 30823446, 2019). "The same consideration holds for recent applications, such as the M:Diabetes mobile application, which was not developed by the same companies that produce the sensors, and aims to be compatible with multiple brands of sensors, insulin pumps, and wearable devices for activity tracking." (PMID 31878195, 2019). "However, these insulin biomarkers might only provide information about insulin resistance in obese individuals; thus, they might not provide reliable information on diabetes outcomes." (PMID 31744179, 2019). "In addition, we do not yet have sufficient individual-level data on new insulin delivery systems and other innovations, including flash monitoring and structured education in diabetes management, to enable a direct assessment of the impact within person before and after changes in treatment." (PMID 31104095, 2019). "Diabetes specifically (type II) has been typified as insulin resistance in which the major organs, liver, adipose and muscle tissues, are not quick to react to the action of insulin, as well as destruction of beta cells of islets of Langerhans which compromised the secretion of insulin produced." (PMID 30680164, 2019). "In addition, this study was also not able to identify all respondents with T2D since the answers were not complete (i.e., a person could state that they use a medicine for treating diabetes, but they did not specify if they used only insulin or not)." (PMID 31286982, 2019). "The proportion of patients with HbA1c or serum glucose level tested was 37.6% in those without diabetes, 48.6% in those with diabetes not receiving medication, 52.9% for those with diabetes receiving noninsulin medication, and 56.8% for those with diabetes receiving insulin." (PMID 31483467, 2019). "However, as hyperglycemia diminishes the cardioprotective effects of insulin, the presence of insulin during IR may have augmented the difference in IR injury between normo- and hyperglycemia in animals without diabetes." (PMID 31151453, 2019). "Diabetes mellitus (DM), which is one of the major noncommunicable diseases worldwide, is a metabolic disorder that results from a defect in insulin production, impaired insulin action, or both." (PMID 31485461, 2019). "Furthermore, the low expression levels of miR-124a in pancreatic islets in subjects without diabetes (in comparison with several other pancreatic islet microRNAs) 14, 20, suggests the need to maintain low miR-124a expression levels in adult insulin-producing cells for proper function." (PMID 31754329, 2019). "Also, consumption of sugar-sweetened beverages (SSB) has been linked to unfavorable metabolic outcomes, and specifically, overconsumption of fructose-sweetened beverages compared to glucose-sweetened beverages decreased insulin sensitivity among overweight and obese individuals without diabetes." (PMID 29914103, 2018). "Diabetes mellitus (DM) is a chronic disease that occurs when the pancreas is no longer able to produce insulin or when the body cannot take full advantage of its insulin." (PMID 29786669, 2018). "While many of these participants may have diabetes of autoimmune aetiology, this was not clinically recognised or apparent, with low-C-peptide participants having late-onset diabetes, raised BMI and time from diagnosis to insulin treatment of several years." (PMID 28983693, 2018).